RNU2-21P (RNA, U2 small nuclear 21, pseudogene)
Gene: Small nuclear RNA gene on chromosome 2 (158,935,798 to 158,935,985, reverse strand). Ensembl gene ENSG00000222300.
Homologues: Orthologues: chimpanzee U2 (100% identical), macaque U2 (95% identical), pig U2 (76% identical), rabbit U2 (34% identical), rat LOC120099534 (34% identical), rabbit U2 (30% identical), tropical clawed frog U2 (27% identical), dog U2 (24% identical), tropical clawed frog U2 (19% identical). Paralogues in human: RNU2-2 (67% identical), U2 (66% identical), RNU2-23P (65% identical), RNU2-59P (65% identical), RNU2-4P (65% identical), U2 (65% identical), RNU2-64P (64% identical), RNU2-6P (64% identical), RNU2-14P (64% identical), RNU2-39P (64% identical), RNU2-43P (64% identical), RNU2-26P (63% identical), and 67 more.